ETV4 (ETS variant transcription factor 4)
Diseases named in the same sentence as ETV4 in open-access papers (continued):
Sharing a sentence is not in itself a finding about the gene and the disease.
tumor (continued). "While we did not see differences in ETV4 expression by tumor site (gastric versus small bowel) or mutation status (PDGFRa versus Kit), though the sample sizes were small for meaningful comparisons, most low-risk, human, primary, untreated GISTs had minimal or undetectable ETV4 expression." (PMID 29371979, 2017). "As with GIST882 cells, ETV4 knockdown in murine S2 GIST cells reduced tumor cell viability and invasion in vitro, as well as tumor growth and Ki-67 staining in vivo." (PMID 29371979, 2017). "After freshly isolating KIT+ and KIT- cells from 3 human metastatic, imatinib-resistant GISTs with high ETV4 expression, we showed that ETV4 mRNA was minimal in KIT- (i.e., non-tumor) cells." (PMID 29371979, 2017). "For example, in PRAD, the most commonly found tumor subgroup has gene fusions involving members of the E26 transformation-specific (ETS) family of TFs, such as ERG, ETV1, ETV4, and FLI1." (PMID 27833659, 2016). "It's worth noting that ETV4, a homologue of ETV1, was elevated in colorectal cancer tissues and enhanced tumor invasion." (PMID 26356816, 2015). "As expected, highly expressed ETV4 in CRMAC increased MMP-7, N-cadherin and vimentin whereas decreased E-cadherin, which promoted tumor invasion." (PMID 26356816, 2015). "In addition, ETV4 has also been found to induce the transcription of uPA, COX2 and SCCA to promote the invasion and metastasis of tumor cells." (PMID 41281746, 2025). "In addition, ETV4 transcriptionally controls the key replisome genes MCM2, ‐4, ‐5, ‐10, and ORC1 expression and affects tumor growth and prognosis of NSCLC patients." (PMID 40548893, 2025). "Indeed, the well-known CIC targets ETV4 and ETV5 are key mediators of tumor cell proliferation and drug resistance." (PMID 41219537, 2025). "While ETV4 generally functions as a pro-tumorigenic factor and correlates with poor prognosis, exceptions such as SKCM highlight the need for integrated analyses that account for tumor-specific molecular features, treatment responses, and genomic landscapes." (PMID 40469297, 2025). "snRNA‐seq analysis revealed that among DUSP4, DUSP6 and ETV4, only DUSP4 was exclusively expressed by cancer cells, making it a more specific biomarker for KC1 tumours, highlighting DUSP4 as a more specific biomarker of KC1 tumours." (PMID 41025426, 2025). "The results indicated that ETV4 knockdown significantly slowed tumor growth without affecting mouse body weight." (PMID 40469297, 2025). "As an important member of the PEA3 subgroup, ETV4 has been found to be overexpressed in multiple cancers and induce cell growth, invasion, and migration, suggesting its essential role in tumor progression." (PMID 38849954, 2024). "Furthermore, ETV4 expression was correlated with immunity, tumor heterogeneity, MMR genes, DNA methyltransferase genes, and tumor stemness in multiple cancers." (PMID 37205199, 2023). "Notably, in PCa, CIC is commonly altered through genomic loss (homozygous and heterozygous deletion) in ~10% of PCa patients and inactivation of CIC de-represses ETV1, ETV4, and ETV5 transcription to promote tumor progression." (PMID 36383412, 2022). "However, ETV4, RNF43 and AXIN2 were clustered with tumour purity and separate from all other infiltrating cell types." (PMID 34824625, 2021). "In this study, the modulated expression of ETV4 in CCA cells was confirmed by RT-real time PCR and immunocytochemistry/immunohistochemistry, both in two tumor cell lines and in mouse tumor tissues that were stimulated by E2, and inhibition by TAM was demonstrated." (PMID 29467595, 2018). "Furthermore, we provide evidence that the silencing of MMP13 inhibits ETV4-induced tumor formation in mice, confirming the in vitro data and highlighting the importance of MMP13 activity in ETV4 tumorigenic functions." (PMID 29996935, 2018).
tumor (continued). "We found that ETV4 is an important oncogenic contributor to GIST since knockdown of ETV4 expression by RNA interference in both human and murine GIST cell lines suppressed tumor cell proliferation and invasion in vitro, as well as tumor growth in vivo." (PMID 29371979, 2017). "We did not detect TMPRSS2-ERG gene fusion in this patient, however, we found that TMPRSS2 gene was fused with other partners including ETV4, TRIP4, and PNPO in the visit 1 patient tumor tissue, and all these TMPRSS2 involved fusion events were rediscovered in PDXs." (PMID 26695660, 2015). "ETV4 is involved in translocations with TMPRSS2 in PCa less often, and, as seen in a GEMM, while ETV4 expression appears not to affect tumor growth per se, it induces metastatic progression in cooperation with activated PI3K pathway." (PMID 25277175, 2014). "ETV-4 on the other hand, was chosen as ETV-4 is known to be rearranged in PCa, similar to ERG, combined with a report showing the occurrence of multiple ETS rearrangements within one prostate gland, within the same tumor focus and within the same nucleus." (PMID 22922762, 2012). "Therefore, ETV4 expression and the expression and distribution pattern of NUT protein can serve as alternative markers for screening this type of tumor, but ultimately, FISH and/or RNA sequencing, as well as methylation testing, are the gold standard for diagnosis." (PMID 40255429, 2025). "Furthermore, Western blotting assay indicated that the expression of NID1 was consistent with ETV4 and LOXL2 in paired non-tumor and tumor tissues samples (n=4), and the correlation analysis on human CRC cDNA array showed that NID1 was positively correlated with ETV4 and LOXL2, respectively." (PMID 41281746, 2025). "Moreover, flow cytometry analyses showed that ETV4 knockdown decreased the percentages of CD11b+Ly6G+ TANs, but not CD11b+F4/80+ TAMs in the footpad tumor." (PMID 36670069, 2023). "Thus, ETV4 and ETV5 may act as key downstream effectors of BRD4 to promote tumor growth and dictate BETi efficacy." (PMID 36475791, 2022). "The prevalence of copy number gains of ETV4 and FAM84B suggests that aberrations involving these genes may be functionally involved in maintaining the disease, or that they occurred early in tumor genesis and inherited by most subclones during tumor expansion." (PMID 21569352, 2011). "Interestingly, MMP13 inhibition disturbs the positive effect of ETV4 on MMT proliferation, migration, and invasion, and we demonstrate that MMP13 acts as a relay of ETV4 in its functional role in the mammary epithelial tumorigenic cells in vitro as well as in tumor graft assays in vivo." (PMID 29996935, 2018). "Consistent with this idea, we find that the expression levels of ETV4, ERG, PIK3CA, and RSPO3 were elevated ~ 80–800-, ~ 25-, ~ 8-, and ~ 10–30-fold compared to the fusion-negative group of the same tumor type, respectively." (PMID 32631391, 2020). "Studies in other tumor types also support an involvement of ETV1 and ETV4 in AIG, but no reference was made regarding the comparative expression of these ETS in the cell models used." (PMID 25595908, 2015). "WT CIC is a transcriptional repressor discovered in Drosophila which is involved in developmental processes and acts as a tumor and metastasis suppressor predominantly through the repression of PEA3 (ETV1, ETV4, and ETV5) family members and negative MAPK pathway (DUSP4/6) regulators." (PMID 39530749, 2024). "Conversely, expression of the GIST lineage survival factor ETV1 did not correlate with mitotic rate or whether a tumor was metastatic (right), although the magnitude of ETV1 mRNA expression was much greater than that of ETV4." (PMID 29371979, 2017).
tumor (continued). "Together, these results showed that the expression of ASCL2 and ETV4 had negative correlation with T cell infiltration in the tumor microenvironment, indicating that overexpression of ASCL2 and ETV4 might inhibit the recruitment and activation of CD8+ T cells in MSS CRC patients." (PMID 33628843, 2021).
cancer (119 papers, 2008 to 2025). A tumor composed of atypical neoplastic, often pleomorphic cells that invade other tissues. "Our findings revealed that ETV4 overexpression is significantly associated with poor prognosis in a range of cancers and regulates cancer progression through multiple mechanisms." (PMID 40469297, 2025). "ETV4 overexpression was detected in several cancer types and was associated with poor prognosis and specific molecular and immune subtypes." (PMID 40469297, 2025). "Using multiple public databases, we investigated the role of ETV4 in the immune response and examined potential associations between ETV4 expression and immune-related molecules in different cancer types." (PMID 40469297, 2025). "Mechanistically, we identified ETV4 as a target gene regulated by enh17, and functional experiments further support ETV4 as a target gene that is involved in cancer-associated phenotypes." (PMID 38849954, 2024). "The present study investigated the role of E twenty-six variant transcription factor 4 (ETV4) among different cancers via pan-cancer analysis." (PMID 37205199, 2023). "Upregulation of ETV4 was associated with poor overall survival, progression free interval, disease-free-interval, and disease specific survival in several cancer types." (PMID 37205199, 2023). "On the other hand, ETV4 activates the sonic Hedgehog signaling, one of the signaling pathways closely associated with cancer stemness, via transcriptionally upregulating the chemokine receptor CXCR4." (PMID 34052833, 2021). "It is also noteworthy that in a recent study of biopsy cores from 120 patients ETV4 expression was mostly associated with high-grade cancer." (PMID 32791988, 2020). "ETV4 overexpression has been implicated in the progression of many types of cancer including esophageal, prostate and breast cancer." (PMID 29467595, 2018). "Our study further clarified that ETV4 has broader applicability across various tumors and confirmed that ETV4 expression is strongly linked to the biological processes of immune-related molecules and immune cells in most cancers." (PMID 40469297, 2025). "As anticipated, the presence of the ETV4 P433L mutation in cancer cells led to a higher incidence of tumor formation compared to the wild type cell lines, the inhibitor XAV-939 could also significantly inhibit this effect." (PMID 39389944, 2024). "Notably, ETV4 has numerous implications as an adverse prognostic factor in multiple cancer types, including ccRCC, which is prominently associated with KDM5C mutations." (PMID 36631623, 2023). "ETV4 expression was highly associated with these four methyltransferases in many cancers." (PMID 37205199, 2023). "In addition, ETV4 also expresses in partial cancer‐associated fibroblasts (CAFs) and endothelial cells (ECs)." (PMID 36670069, 2023). "Therefore, our study will help to advance and accelerate the understanding ETV4-associated human cancers." (PMID 36289913, 2022). "Moreover, ALDH activity, a hallmark of cancer stem cells, was significantly increased or decreased in cells with overexpression or knockdown of ETV4, respectively." (PMID 26356813, 2015). "However, no study has yet demonstrated whether there is an enhancer region associated with ETV4 that affects the expression or function of ETV4 as well as contributes to cancer risk or progression." (PMID 38849954, 2024). "Among them, Cspg5, Fbn1, Thbs1, Pdpn, Etv4, Unc5a, Ntn1, and Nat8l were associated with the OC prognosis; Cspg5, Fbn1, Pdpn, and Unc5a were correlated with patient age; Fbn1, Mycn, Nat8l, Unc5a, and Ntn1 were significantly correlated with individual cancer stage." (PMID 36829196, 2023). "This study provides valuable insights into the role of ETV4 in cancer and identifies potential strategies to enhance cancer immunotherapy." (PMID 40469297, 2025). "In cancer, ETV4 regulates genes that control cell proliferation and migration and can also activate multiple matrix metalloproteinase (MMP) genes to promote cancer cell invasion." (PMID 40469297, 2025).
cancer (continued). "In Ras/MAPK mutant cancers, a conserved gene signature that includes ETV4/5, SPRY2/4, DUSP4/6, and EPHA2/4 is a reliable biomarker of pathway activation and is associated with good clinical response to MEK inhibitor therapy." (PMID 41446112, 2025). "Based on public databases and our experimental validation, we systematically investigated the role of ETV4 in various cancers." (PMID 40469297, 2025). "Further validation in clinical samples and functional studies is warranted to clarify the biological role of ETV4 and its potential utility as a therapeutic target or prognostic indicator in pan-cancer." (PMID 40469297, 2025). "In 18 types of cancers with paired sample analysis, ETV4 mRNA expression was generally increased, except in KIRC, PRAD, and KICH." (PMID 40469297, 2025). "We utilized heat maps constructed with data on immune cells and immune factors to investigate the relationship between ETV4 expression and immune infiltration, as well as immune regulation across various cancers." (PMID 40469297, 2025). "In conclusion, our study clarified the role of ETV4 in pan-cancer contexts from different perspectives, including its related signaling pathways, its relationship with immune cell infiltration, and its mutation sites." (PMID 40469297, 2025). "The activation of MMP1 and RAS/MAPK signaling have been reported to be involved in the regulation of ETV4 in cancer cells." (PMID 38849954, 2024). "Mechanistically, this enhancer is bound by the key transcriptional regulator STAT3 and promotes ETV4 expression, ultimately leading to cancer-related phenotypes." (PMID 38849954, 2024). "ETV4 is well characterized as a cancer-driven gene that is aberrantly activated in a variety of cancers, including gastric cancer, lung cancer, hepatocellular carcinoma, prostate cancer and colorectal cancer, and it facilitates tumorigenesis and metastasis." (PMID 38849954, 2024). "Changes in down-regulated genes were ETV4 (ETS Variant Transcription Factor 4) and ETV5 (ETS Variant Transcription Factor 5) are related to transcriptional regulation, EML4 (EMAP like 4), BCL2 and Myc are related to cancer development." (PMID 39834948, 2024). "According to our model, ETV4 shows maximal expression in stage 4 and is concordant with a molecular basis for cancer stages." (PMID 39484215, 2024). "In the present study the potential function of ETV4 in various cancers was investigated using pan-cancer analysis." (PMID 37205199, 2023). "Recent studies revealed that ETV4 is aberrantly expressed in many types of tumors, and its overexpression is related to poor prognosis of cancer patients, including breast, prostate, lung, and gastric cancers." (PMID 37205199, 2023). "The present study surveyed the effects of ETV4 on cancer using RNA sequencing data obtained from The Cancer Genome Atlas and GTEx, and further explored its role in drug sensitivity using data from Cellminer." (PMID 37205199, 2023). "In terms of metabolism, ETV4 activates PPARγ signaling, which directly regulated glycolysis and fatty acid metabolism in cancer cells." (PMID 37692839, 2023). "ETV4 and ETV5 have been previously implicated in mediating progression of disease in a variety of cancer systems." (PMID 36509998, 2023). "ETV4 expression was also compared with immunity, heterogeneity, stemness, mismatch repair genes, and DNA methylation among different cancers." (PMID 37205199, 2023). "RNA-seq data from TCGA were used to assess the relationship between ETV4 expression and cancer heterogeneity." (PMID 37205199, 2023). "ETV4 overexpression has been correlated with the activation of cancer-related genes relevant to cell proliferation and to invasiveness." (PMID 37002241, 2023). "Expression of endogenous retroviruses envelope protein in different human cancer cell lines was observed to induce the transcription of ETV4 and ETV5, which are downstream effectors of the MAPK ERK1/2." (PMID 37234529, 2023).